NLRC4 (NLR family CARD domain containing 4)
Diseases named in the same sentence as NLRC4 in open-access papers (continued):
Sharing a sentence is not in itself a finding about the gene and the disease.
keratitis (4 papers, 2017 to 2024). A corneal disease that is characterized by inflammation of the cornea. "In contrast, in a model of Pseudomonas induced keratitis utilizing B6 (susceptible) and NLRC4-/- (on the B6 background) mice, IL-1beta processing was found to be independent of NLRC4 or caspase-1 activity for both cytotoxic and invasive strains." (PMID 28961278, 2017). "Preventing the production of IL-1β during P. aeruginosa keratitis by silencing the gene for ﻿the inflammasome NLRC4, inhibiting caspase-1 production (either using gene knockout mice or antibodies), or administering IL-1Ra (a natural inhibitor of IL-1β) reduces the clinical pathology of keratitis." (PMID 36422638, 2022). "Using the NLRP3 inhibitor MCC950, Nlrp3-/- mice, and Nlrc4-/- mice, we also demonstrate that NLRP3 rather than NLRC4 is required for bacterial killing and preventing corneal perforation in P. aeruginosa keratitis." (PMID 37730693, 2023). "In a series of 26 patients with NLRC4-AD, conjunctivitis, episcleritis, keratitis, dry eye have been reported in 42% of patients, and were only present in the FCAS4 subgroup (61.1%), while no cases were found in patients with NLRC4-MAS." (PMID 38984133, 2024).
Legionella infection (4 papers, 2015 to 2023). "In animal models of Legionella infection, it has indeed been proven that the NLR family CARD domain containing 4 (NLRC4) inflammasome drives pyroptosis through caspase-1 activation and IL-18 release." (PMID 37965258, 2023).
lung adenocarcinoma (4 papers, 2020 to 2023). A carcinoma that arises from the lung and is characterized by the presence of malignant glandular epithelial cells. "KEY POINTS: A lung adenocarcinoma patient harboring concurrent NLRC4-ALK and EML4-ALK fusion mutations benefited from crizotinib after surgery." (PMID 32212216, 2020). "Further, we validated the expression level of CHMP2A and NLRC4 in 16 cases of lung adenocarcinoma and matched adjacent cancerous tissues by using qRT-PCR analysis." (PMID 37077542, 2023). "And our experimental data from H1299 (lung adenocarcinoma cell line) showed that overexpression of NLRC4 could promote pyroptosis by measuring LDH released from dead cells." (PMID 36437954, 2022). "For instance, Wang and colleagues recently reported a five-autophagy-related signature (ITGB4, NLRC4, ATG9B, CDKN2A, ERO1A) based on overall survival in patients with lung adenocarcinoma." (PMID 34252349, 2021). "Here, we report a case of a 64-year-old Chinese woman who was diagnosed with lung adenocarcinoma (ADC) who concurrently harbored two types of ALK-rearrangements, including an unreported NLRC4-ALK fusion and EML4-ALK fusion." (PMID 32212216, 2020).
Neonatal onset multisystem inflammatory disease (4 papers, 2021 to 2023). "To date, no other case of somatic mosaicism of NLRC4 has been reported, nor has NLRC4 been reported as the causative gene of CINCA syndrome." (PMID 33535645, 2021).
non-alcoholic steatohepatitis (4 papers, 2021 to 2024). "Recently, it is reported that NLR family CARD domain-containing protein 4 (NLRC4) inflammasome was found to mediate the pyroptosis of hepatocytes in non-alcoholic steatohepatitis (NASH)." (PMID 35634294, 2022). "SMS1 triggered nonalcoholic steatohepatitis by regulating NLRC4-dependent hepatocyte pyroptosis." (PMID 39187376, 2024).
systemic juvenile idiopathic arthritis (4 papers, 2021 to 2024). "Like systemic-onset JIA, NLRC4 GOF shares similarities with familial hemophagocytic lymphohistiocytosis." (PMID 34640385, 2021). "Our study also revealed that the serum Gal-3 levels were highly correlated with the serum IL-18 levels, which are presumed to be useful biomarkers for autoinflammatory diseases, such as AOSD, systemic juvenile idiopathic arthritis, and NLRC4 inflammasomopathies." (PMID 38711500, 2024).
tuberculosis (4 papers, 2013 to 2023). A chronic, recurrent infection caused by the bacterium Mycobacterium tuberculosis. "Both TLR5 and NLRC4 were upregulated in melioidosis (P = 5.4 × 10–13 and 4.2 × 10–10, respectively), but both were upregulated in tuberculosis also (P = 8.1 × 10–10 and 2.4 × 10–11)." (PMID 23383015, 2013). "And NLRC4 signaling contributes to several bacteria-induced lung inflammation, even tuberculosis." (PMID 37194062, 2023). "In another study, also in an Ethiopian cohort of HIV co-infected TB patients, 7 genes (FCGR1A, RAB24, TLR1, TLR4, MMP9, NLRC4, and IL1B) accurately discriminated between active tuberculosis disease and latent infection." (PMID 33692804, 2021).
type 2 diabetes (4 papers, 2018 to 2025). "RKIP negatively regulates NLRP1 activation and NLRP3 and NLRC4-induced inflammatory body formation and plays an important role in the pathogenesis of type 2 diabetes." (PMID 36017103, 2022). "Another NLR protein, NLR family CARD domain-containing protein 4 (NLRC4), has been observed in heart diseases, and this study showed that NLRC4 inflammasome was hyperactivated by mitochondrial DNA in cardiomyocytes in a type 2 diabetes mouse model after MI." (PMID 29576748, 2018). "Glyburide, a common drug for type 2 diabetes (T2D) treatment, was the first identified NLRP3 inhibitor, though it does not inhibit NLRP1 or NLRC4-dependent IL-1β production." (PMID 41280719, 2025).
acute myeloid leukemia (3 papers, 2022 to 2025). Acute myeloid leukemia (AML) is a group of neoplasms arising from precursor cells committed to the myeloid cell-line differentiation. "Conversely, in acute myeloid leukemia (AML) cell lines, curcumin has been found to activate the NLRC4, AIM2, and IFI16 inflammasomes, inducing pyroptosis through the upregulation of the ISG3 transcription factor." (PMID 40725015, 2025). "In models of acute myeloid leukemia (AML), curcumin appears to operate through a non-canonical inflammasome pathway by upregulating interferon-stimulated gene ISG3, thereby activating NLRC4, AIM2, and IFI16 inflammasome sensors." (PMID 40806716, 2025).
Autoimmune Thyroiditis (3 papers, 2018 to 2021). "A study explored the link between inflammasomes and autoimmune thyroiditis, and revealed the activation of NLRP1, NLRC4, and AIM2 inflammasomes in the thyroid tissues from patients with AIT." (PMID 34234669, 2021). "Correlation between NLRP3, NLRP1, NLRC4, absent in melanoma 2 (AIM2), ASC, caspase-1, IL-1β, and IL-18 expression in the autoimmune thyroiditis group." (PMID 29915579, 2018).
chronic heart failure (3 papers, 2023 to 2025). "NLRC4 activation has been documented in human chronic heart failure and in rodents and pigs using different chronic heart failure models." (PMID 40332346, 2025). "A study comparing the serum levels of IL-1β in normal patients and those with chronic heart failure classified into functional classes II, III, and IV found that both IL-1β and NLRC4 expression levels increased in the chronic heart failure group." (PMID 39687084, 2024). "Moreover, non-NLRP3 inflammasomes, including NLRC4 and AIM2, contribute to the development of chronic heart failure." (PMID 37239853, 2023).
dermatitis (3 papers, 2020 to 2023). An inflammatory process affecting the skin. "Among all NLR members (22 up to now), NLRP3, NLRP1, NLRC4, and NLRP6 represent the most studied inflammasomes, involved in many inflammatory tissues pathologies, where NLRP3, NLRP1, and NLRC4 are mainly related to autoinflammatory skin disorders." (PMID 38068996, 2023).
fungal infection (3 papers, 2011 to 2025). "It is speculated that NLRC4 may not recognize fungal PAMPs directly; instead, its activation could be indirectly modulated by bacterial dysbiosis resulting from fungal infection that introduces bacterial ligands known to activate NAIPs and NLRC4." (PMID 41249509, 2025). "Further studies are warranted to determine whether NAIPs are capable of recognizing components derived from fungi, or if the activation of the NLRC4 inflammasome during fungal infection depends on secondary signals originating from bacterial cohabitants or host factors induced by the fungus." (PMID 41249509, 2025). "Therefore, we hypothesized that the impact of NLRC4 activation during fungal infection was manifested in mucosal and/or stromal tissues versus hematopoietic cells." (PMID 22174673, 2011). "With respect to inflammasome activation upon fungal infections, only the inflammasome receptors AIM2, NLRC4 and, mainly, NLRP3, are related to engaging and triggering IL-1β caspase-dependent cleavage." (PMID 29209318, 2017). "Although limited in vitro studies using NLRC4 deficient macrophages or dendritic cells challenged with Candida albicans revealed no defects in caspase-1-dependent IL-1β responses, the role of NLRC4 in live fungal infection models has not been thoroughly defined." (PMID 22174673, 2011). "Thus, negative control of NLRP3 activation by NLRC4/IL1Ra reduces inflammatory response, but allows host cells to control fungal infection." (PMID 41249509, 2025).
HIV-1 infection (3 papers, 2021 to 2023). The type species of lentivirus and the etiologic agent of acquired immunodeficiency syndrome (AIDS). "Except for NLRP3 and PYHIN, which were reported more frequently, NLRP1, NLRC4 and NLRC5 inflammasome can also be activated by HIV-1 and are closely associated with HIV-1 infection." (PMID 37465759, 2023). "The STORM data demonstrated that NAIP–gp41 complexes colocalize with NLRC4 providing further evidence that upon HIV-1 infection, gp41 forms clusters with NAIP and NLRC4 where it triggers inflammasome activation leading to IL-18 secretion." (PMID 33861800, 2021). "To date, activation of multiple inflammasomes including NLRP3, NLRC4 and IFI16 has been reported in HIV-1 infection, while numerous studies have also found that HIV-1-induced inflammatory responses and pyroptosis are also dependent on inflammasome." (PMID 37465759, 2023). "To show evidences of early inflammasome sensing of HIV-1 in huNSG mice upon HIV-1 infection, we quantified mRNA expression of genes involved in inflammasome activation (NLRP3, NLRP1, NLRC4, AIM2, IFI16, ASC, CASP1, IL1Β, and IL18) in hCD45+ cells from multiple tissues collected at necropsy." (PMID 36800238, 2023).
Hyperglycemia (3 papers, 2016 to 2023). An increased concentration of glucose in the blood. "The blood glucose level rose both in wild-type (WT) and Nlrc4-/-mice one week after STZ treatment and hyperglycemia persisted during the 8-week period." (PMID 27706238, 2016).
inflammatory bowel disease (3 papers, 2021 to 2024). A spectrum of small and large bowel inflammatory diseases of unknown etiology. "The activity of multiple inflammasomes has been implicated in inflammatory bowel disease in the regulation of commensal microbiota, while NLRP3, NLRP6, and NLRC4 expression can influence tumor formation." (PMID 34903717, 2021). "Furthermore, NLRC4 plays a crucial role in maintaining the microbial community balance and safeguarding the intestinal mucosal barrier, preventing the overgrowth of harmful microbes and the onset of gastrointestinal diseases such as inflammatory bowel disease." (PMID 39292002, 2024). "The Genomics England R15 primary immunodeficiency and monogenic inflammatory bowel disease gene panel of 429 genes did not reveal any pathogenic variants, including genes known to be associated with high IL-18 levels and inflammation such as NLRC4 or XIAP." (PMID 39458007, 2024).
injury (3 papers, 2021). Damage inflicted on the body as the direct or indirect result of an external force, with or without disruption of structural continuity. "Substantial evidence has been indicated that NLRP3 and NLRC4 inflammasomes possess well-characterized protective functions in alcoholic-induced liver injury." (PMID 33406504, 2021). "Altogether, these results showed that NLRC4 may aggravate ICH-induced brain injury in rats." (PMID 34848837, 2021).
intestinal infection (3 papers, 2013 to 2023). "Upon infection with pathogenic bacteria, intestinal phagocytes produce mature IL-1β through the NLRC4 inflammasome and mice deficient in NLRC4 or IL-1β receptor are highly susceptible to intestinal infection." (PMID 23606794, 2013). "However, elevated IL-18 levels in NLRC4V341A-expressing mice did not induce intestinal pathology and did not impact on gastrointestinal infections with NLRC4-activating pathogens." (PMID 38090573, 2023).
intracerebral hemorrhage (3 papers, 2021 to 2023). A cerebrovascular disorder characterized by bleeding into one or both cerebral hemispheres including the basal ganglia and the cerebral cortex. "Herein, we have investigated the role of NK1R receptor inhibition using Aprepitant to attenuate NLRC4-dependent neuronal pyroptosis after intracerebral hemorrhage (ICH), as well as the underlying mechanism." (PMID 35922848, 2022). "The aim of the study was to discern the potential ability of serum NLRC4 in assessment of prognosis after intracerebral hemorrhage (ICH)." (PMID 36970543, 2023). "We concluded that NLRC4 inflammasomes are involved in intracerebral hemorrhage-induced inflammation." (PMID 34848837, 2021). "We explored whether NLRC4 knockdown alleviated inflammatory injury following intracerebral hemorrhage (ICH)." (PMID 34848837, 2021). "Overall, our results indicated that NLRC4 may result in the aggravation of intracerebral hemorrhage-related inflammation." (PMID 34848837, 2021). "Furthermore, our research provided novel insights into the NLRC4 inflammasome after intracerebral hemorrhage and suggested the role of RGS2 in NLRC4 inflammasome activation by LRRK2 after ICH." (PMID 34848837, 2021).
liver disease (3 papers, 2013 to 2025). "By characterizing the Nlrc4 inflammasome and its association to liver regeneration we have potentially provided new insights for treatment of liver disease." (PMID 26635450, 2015).
memory impairment (3 papers, 2020 to 2022). "NLRC4 inflammasome, via IL-1β and IL-18, contributes to memory impairment and neuroinflammation in a rat model of Alzheimer-like disease." (PMID 33584697, 2020). "Lastly, aberrant activation of NLRC4 is evident in non-alcoholic fatty liver disease, memory impairment in Alzheimer-like disease, myocardial infarction, and coronary stenosis." (PMID 33584697, 2020). "For instance, the activation of NLRC4 inflammasome interacts with CASP1, IL-1β, and p-Tau to contribute to neuroinflammation and memory impairment." (PMID 35783533, 2022).
periodontitis (3 papers, 2017 to 2024). An acute or chronic inflammatory process that affects the tissues that surround and support the teeth. "NLRC4 may have protective roles in A. actinomycetemcomitans-induced periodontitis; however, P. gingivalis infection was shown to not activate NLRC4 inflammasomes in THP-1 macrophages and gingival epithelial cells." (PMID 34177950, 2021).
primary immunodeficiency (3 papers, 2022 to 2025). "NLRC4 was related to the cell intestinal immune network for IgA production, complement and coagulation cascades, antigen processing and presentation, primary immunodeficiency, adhesion molecules cams, and ribosome." (PMID 36685920, 2022).
salmonellosis (3 papers, 2012 to 2014). Infections with bacteria of the genus salmonella. "recently showed that Nlrp3/Nlrc4 double knockout mice have a markedly increased susceptibility for invasive salmonellosis when compared to WT controls." (PMID 25115174, 2014). "Potential immunomodulating treatment strategies for invasive Salmonellosis could target the pathogen directly (e.g., based on drugs targeting T3SS or flagella) or target key host response proteins (e.g., TLR4, NLRC4, or IL-1β) depending on the phase of the immune response." (PMID 23055923, 2012).
systemic lupus erythematosus (3 papers, 2021 to 2025). An autoimmune multi-organ disease typically associated with vasculopathy and autoantibody production. "For example, patients with NLRC4-associated autoinflammatory syndrome presenting with joint pain, fevers, and rashes may be evaluated by rheumatologists for systemic lupus erythematosus (SLE) or systemic juvenile arthritis." (PMID 40842819, 2025). "Patients with systemic lupus erythematosus (SLE) suffer from disordered Th1/Th2 and Treg/Th17 balances, evidence has demonstrated that NLRP3, NLRP1, NLRC4, and AIM2 were involved in the regulation of Th1, Tfh, and Th17 cell-mediated immune responses." (PMID 38177104, 2024).
acute myocardial infarction (2 papers, 2020 to 2025). Necrosis of the myocardium, as a result of interruption of the blood supply to the area. "The role of NLRP1 and NLRC4 inflammasomes after acute myocardial infarction (MI) is poorly understood." (PMID 40332346, 2025).
Allergy (2 papers, 2023 to 2024). An allergy is an immune response or reaction to substances that are usually not harmful. "However, to really understand the role of NLRP3 in BP allergy as well as in other allergic disorders, a cell type-specific knockout or knock-in similar to what has already been established for the NAIP/NLRC4 inflammasome would be beneficial." (PMID 38933263, 2024).
aspergillosis (2 papers, 2016 to 2022). Aspergillosis is an infection, growth, or allergic response caused by the Aspergillus fungus. "Our study showed that TT homozygote was associated with a decreased risk of aspergillosis, reflecting the role of NLRC4 in host defense against Aspergillus infection as well." (PMID 35407478, 2022). "For the NLRC4 rs212704, the TT homozygote was associated with a lower risk of aspergillosis (p = 0.0447; OR = 0.4468, 95%CI: 0.2071 to 0.959) while for the NLRC5 rs1684579 it was opposite (p = 0.0261; OR = 2.066, 95%CI: 1.085 to 4.018)." (PMID 35407478, 2022). "Our study demonstrated that the polymorphisms of NLRs (NLRP3, NLRC4, NLRC5) were associated with pulmonary aspergillosis risk, but there were still some limitations." (PMID 35407478, 2022). "A total of 4 SNPs (NLRP3 rs3806265, NLRC4 rs212704, NLRC5 rs1684579, and rs12598522) were observed an association with aspergillosis risk." (PMID 35407478, 2022). "In our study, we found the TT homozygote of rs212704 in NLRC4 and C allele of rs12598522 in NLRC5 was associated with a lower risk of aspergillosis." (PMID 35407478, 2022). "A total of eight SNPs (NLRP3 rs3806265, NLRC4 rs212704 and NLRC5 rs1684579, rs12598522, rs3995817, rs3995818, rs34531240, rs28438857) were observed an association with susceptibility of pulmonary aspergillosis." (PMID 35407478, 2022). "Our results identified the association of NLRP3, NLRC4, and NLRC5 genetic variation with the susceptibility of pulmonary aspergillosis for the first time." (PMID 35407478, 2022). "In aspergillosis, we found that NLRC4 activation occurs through the TLR5/NAIP5/NF-κB-dependent pathway." (PMID 26972847, 2016). "In an aspergillosis mouse model, several kinds of NLRs increased in the infected lungs, including NLRP3, NLRC4, and NLRC5, but their exact functions remain to be explored." (PMID 35407478, 2022). "For the first time, we found rs3806265 in NLRP3, rs212704 in NLRC4 and rs12598522, rs34531240, rs28438857, rs3995818, rs3995817, rs1684579 in NLRC5 were associated with pulmonary aspergillosis in non-neutropenic patients." (PMID 35407478, 2022). "In this study, we investigated 16 SNPs in NLRP3, NLRC4, and NLRC5 genes among the southeastern Han Chinese population and analyzed the relationships between these SNPs and susceptibility of pulmonary aspergillosis in non-neutropenic patients." (PMID 35407478, 2022). "The aim of this study was to investigate the relationship between NLRP3, NLRC4, and NLRC5 gene polymorphisms and susceptibility to pulmonary aspergillosis in non-neutropenic patients among the Chinese population." (PMID 35407478, 2022).